CLIC6 (CLIC family member 6)
Description:
In the soluble state, catalyzes glutaredoxin-like thiol disulfide exchange reactions with reduced glutathione as electron donor (By similarity). Can insert into membranes and form voltage-dependent chloride-selective channels. The channel opens upon membrane depolarization at positive voltages and closes at negative membrane voltages. May play a critical role in water-secreting cells, possibly through the regulation of chloride ion transport (By similarity).
Synonyms: CLIC1L; CLIC5
Tractability: Antibody: UniProt places it where antibodies can reach, with medium confidence; UniProt predicts a signal peptide or a membrane-spanning region; its Gene Ontology location is reachable by antibodies, with medium confidence. PROTAC: ubiquitination databases record sites on it.
Gene: Protein-coding gene on chromosome 21 (34,668,994 to 34,718,227, forward strand). Ensembl gene ENSG00000159212.
Subcellular location: Cytoplasm; Cell membrane
Gene Ontology:
Molecular function: chloride channel activity; D2 dopamine receptor binding; D3 dopamine receptor binding; D4 dopamine receptor binding
Biological process: chloride transmembrane transport
Cellular component: extracellular exosome; cytoplasm; plasma membrane
Genetic constraint (gnomAD): Loss-of-function variants: 36 observed, 32.89 expected, observed/expected ratio (o/e) 1.09, 90% interval 0.84 to 1.45. The synonymous counts are far from expectation, so gnomAD's model fits this gene poorly and the ratio says little. Missense variants: 959 observed, 760.56 expected, observed/expected ratio (o/e) 1.26, 90% interval 1.2 to 1.33. Synonymous variants: 439 observed, 342.44 expected, observed/expected ratio (o/e) 1.28, 90% interval 1.18 to 1.39.
Homologues: Orthologues: chimpanzee CLIC6 (92% identical), macaque CLIC6 (91% identical), pig CLIC6 (60% identical), rat Clic6 (59% identical), mouse Clic6 (58% identical), dog CLIC6 (57% identical), tropical clawed frog clic6 (39% identical), zebrafish clic6 (27% identical), Caenorhabditis elegans exl-1 (11% identical), Drosophila melanogaster Clic (10% identical), Caenorhabditis elegans exc-4 (10% identical), Drosophila melanogaster GstT1 (6% identical), and 17 more. Paralogues in human: CLIC4 (27% identical), CLIC5 (26% identical), CLIC2 (23% identical), CLIC1 (23% identical), CLIC3 (17% identical), EEF1G (8% identical), GSTT2 (7% identical), GSTT2B (7% identical), GDAP1 (7% identical), GSTT4 (7% identical), GSTZ1 (7% identical), GSTO1 (6% identical), and 2 more.
Diseases named in the same sentence as CLIC6 in open-access papers:
CLIC6 is named in the same sentence as 22 diseases in open-access papers, as found by Europe PMC text mining. Sharing a sentence is not in itself a finding about the gene and the disease. The quoted sentences say what the papers report.
breast carcinoma (10 papers, 2013 to 2025). "Aligned with this study’s findings, Liu demonstrated that elevated CLIC6 expression in breast cancer patients is associated with improved survival outcomes compared to those with lower expression levels, indicating its role as a protective factor." (PMID 41142627, 2025). "Western blotting confirmed CLIC6 protein levels in breast cancer samples, while CCK-8, colony formation, transwell, and scratch assays evaluated its role in cell proliferation and migration." (PMID 41142627, 2025). "The findings from the qRT-PCR and WB analyses demonstrated that CLIC6 was downregulated in breast cancer tissue." (PMID 41142627, 2025). "Previous studies have found that CLIC6 is overexpressed in breast cancer and endometrial cancer." (PMID 36072012, 2022). "CLIC6 is a member of the intracellular chloride channels consisting one of the dopamine receptor-mediated signaling pathways and has changed its expression in breast cancer." (PMID 34092242, 2021). "adrenomedullin-2 (ADM2) is a hypoxia-inducible endothelial peptide that stabilizes pulmonary microvascular.CLIC6 is a member of the intracellular chloride channel, one of the dopamine receptor-mediated signalling pathways, and is differentially expressed in breast cancer." (PMID 34804921, 2021). "The low expression of CLIC6 in breast cancer is related to a high histological grade 34." (PMID 33758613, 2021). "Moreover, this study conducted an in-depth investigation into the potential pathways through which CLIC6 may contribute to the development of breast cancer." (PMID 41142627, 2025). "For breast cancer, we find out that HSPA2A, RNASE1, CLIC6, and IFITM1 are highly expressed in some specific groups." (PMID 33133130, 2020). "For breast cancer, we select five essential genes, such as CTSA, HSPA2, RNASE1, CLIC6, IFITM1." (PMID 33133130, 2020). "Among the listed genes, BIRC5, SEC14L2, Thymidine kinase (TK1), ZNF385B, CLIC6, ELOVL1, CHAF1B and TFF1 have been reported to have a role in early detection of cancers, tumor progression and metastasis in most of cancer types including breast cancer." (PMID 31703592, 2019).
lung carcinoma (4 papers, 2021 to 2025). "The results showed that CLIC6 protein levels were higher in UCEC, lung cancer, and PAAD compared to normal tissues; however, CLIC6 protein levels were lower in HNSC and liver cancer." (PMID 41142627, 2025). "Thirty one down-regulated genes are known to be prognostic markers of lung cancer, 28 of which are of favorable prognosis, such as GDPD1, SLC46A3, CLIC6, LZTS3 or CCNO." (PMID 36544755, 2022). "Compared with normal tissues, the expression of ADM2, CLIC6, KIF20A, LAD1, MUC5B, and TNS4 was up-regulated, and the expression of ATG16L2, KCNK3, MAFF, NKD1, and SPATA13 was down-regulated in lung cancer tissues." (PMID 34804921, 2021). "In our study, the expression of CLIC6, CLDN2, and BPIFB1 was significantly upregulated in H1975 and A549 cells, suggesting that high expression of these genes may influence the progression of lung cancer through immune regulation." (PMID 40399547, 2025).
Alzheimer disease (2 papers, 2018 to 2023). A progressive, neurodegenerative disease characterized by loss of function and death of nerve cells in several areas of the brain leading to loss of cognitive function such as memory and language. "Furthermore, members of the CLIC family, CLIC1 to CLIC6 are also involved in pathological conditions, like cancer initiation and progression, cardiac dysfunction, and Alzheimer’s Disease (AD)." (PMID 37601094, 2023).
lung adenocarcinoma (2 papers, 2021 to 2026). A carcinoma that arises from the lung and is characterized by the presence of malignant glandular epithelial cells. "Recent studies have reported evidence that CLIC6 expression is significantly associated with lung adenocarcinoma prognosis." (PMID 34804921, 2021).
adenoid cystic carcinoma (1 paper, 2020). A malignant tumor arising from the epithelial cells. "Recently, hypermethylation islands are discovered in the promoter regions of CLIC6 in a study that identified epigenetic CpG island methylation in adenoid cystic carcinoma, suggesting CLIC6 being involved in the development of this tumor and may serve as a diagnostic marker." (PMID 32116799, 2020).
Anxiety (1 paper, 2022). Intense feelings of nervousness, tension, or panic often arise in response to interpersonal stresses. "Notably, gastrointestinal vagal deafferentation affected genes previously associated with anxiety modulation in the mouse amygdala (Cldn2, Mfrp, Ttr, F5, Clic6), although in opposite direction compared with acute or early-life stressors." (PMID 35965105, 2022).
epilepsy (1 paper, 2021). A brain disorder characterized by episodes of abnormally increased neuronal discharge resulting in transient episodes of sensory or motor neurological dysfunction, or psychic dysfunction. "Furthermore, the hub genes of each AD- and epilepsy-associated GCM were captured, including TRPC1, C2ORF40, NR3C1, KIAA0368, MMT00043109, STEAP1, MSX1, KL, and CLIC6." (PMID 34697589, 2021). "Furthermore, the hub genes of AD- and epilepsy-associated GCMs were captured by weighted key driver analysis (wKDA), including TRPC1, C2ORF40, NR3C1, KIAA0368, MMT00043109, STEAP1, MSX1, KL, and CLIC6." (PMID 34697589, 2021).
tumor (11 papers, 2014 to 2026). "Chloride Intracellular Channel 6 (CLIC6) is a potential cancer therapy target due to its close association with tumor development." (PMID 41142627, 2025). "In conclusion, CLIC6 can serve as a key biomarker for various cancers, and its expression level is related to the tumor immune microenvironment and the outcomes in selected cancers; further validation is warranted." (PMID 41142627, 2025). "Subsequently, this study examined the relationship between CLIC6 expression and immune cell infiltration in the tumor microenvironment across different cancer types." (PMID 41142627, 2025). "Our research on CLIC6 in BRCA has revealed new potential for tumor treatment strategies targeting this marker." (PMID 41142627, 2025). "The results showed that the CLIC6 promoter exhibited high methylation levels in most tumors, consistent with most tumor suppressor genes, and CLIC6 promoter methylation levels were inversely related to CLIC6 mRNA expression." (PMID 41142627, 2025). "For example, three chloride intracellular channel genes (CLIC3, CLIC4, and CLIC5) were down-regulated, while CLIC6 was up-regulated three-fold in tumor tissues." (PMID 24466154, 2014). "Additionally, CLIC6 contributes to the regulation of ion transport, signaling within cells, and the tumor microenvironment across various cellular functions." (PMID 41142627, 2025). "PRMTs may promote tumor development by influencing immune escape through the CLIC6/CLDN2/BPIFB1 axis." (PMID 40399547, 2025). "In summary, this study suggests that CLIC6 may regulate tumor immune effects, making it a potential target for novel tumor immunotherapy." (PMID 41142627, 2025). "However, this study found that CLIC6 exhibits low expression levels in these tumors, suggesting it may negatively impact patient prognosis by reducing tumor immune scores and suppressing the activation of immune-related genes." (PMID 41142627, 2025). "Combined with its expression levels in BRCA, this further validated the hypothesis that the absence of CLIC6 expression is associated with the loss of anti-tumor immune effects." (PMID 41142627, 2025). "Analysis of Human Protein Atlas and The Cancer Genome Atlas data related to CLIC1 expression in ccRCC and the tumor endothelium revealed that CLIC1, along with CLIC6, are reported to be expressed in both normal and ccRCC human kidney tissues." (PMID 36497464, 2022). "The following marker genes were differentially expressed in the triphasic tumours relative to the blastemal tumours: PA (LHX1), RV/CSB/SSB (BMP2, CDH6, JAG1, PAPSS2), ePT and/or imHL (CIDEB, CLIC6, UNC5CL, VDR), and early DT/imHL (KCNJ1)." (PMID 29040332, 2017). "Further in-depth studies regarding the roles in the tumor process are required for CLIC5 and CLIC6." (PMID 32116799, 2020). "However, CLIC6 has no reported significance in tumorigenesis and tumor progression to date." (PMID 36915125, 2023). "We found that the correlation of expression for CLIC6 and RAB30 in neighboring cells is higher in the ER+/PR+ group, while the correlation of expression for KLRD1 and LTB is higher in the ER‐/PR‐ group, regardless of whether the tumor is detected in the early or late stage." (PMID 40420636, 2026).
cancer (8 papers, 2019 to 2025). A tumor composed of atypical neoplastic, often pleomorphic cells that invade other tissues. "The findings indicated a positive correlation between CLIC6 mRNA expression levels and the infiltration levels of cancer-associated fibroblasts in the majority of cancer types." (PMID 41142627, 2025). "In short, low CLIC6 expression is linked to poor outcomes in various cancers, making it a potential biomarker for predicting prognosis in pan-cancer patients." (PMID 41142627, 2025). "Subsequently, the relationship between CLIC6 mutations and CLIC6 mRNA expression, as well as their association with prognosis in pan-cancer patients, was investigated using the GSCA database." (PMID 41142627, 2025). "This study was the first to highlight the significant role of CLIC6 mutations in pan-cancer, but additional experimental investigations are required to elucidate the mechanisms through which CLIC6 mutations affect cancer development and progression." (PMID 41142627, 2025). "Due to CLIC6 amplification mutations and high levels of CLIC6 mRNA expression, patients with various cancers have poorer prognoses." (PMID 41142627, 2025). "This study found that CLIC6 mutations are present in certain types of cancer, and they are positively correlated with CLIC6 mRNA expression levels." (PMID 41142627, 2025). "CLIC6 mutations are common in many cancers and affect prognosis." (PMID 41142627, 2025). "Therefore, this study speculates that CLIC6 amplification mutations are an important cause of elevated CLIC6 mRNA expression levels, resulting in poor outcomes for cancer patients." (PMID 41142627, 2025). "Additionally, in most malignant tumors, CLIC6 expression was positively linked to m6A methylation regulators, with a strong positive correlation observed with THYM, suggesting that CLIC6 may exhibit elevated m6A methylation levels in THYM." (PMID 41142627, 2025). "Thus, CLIC6 mutations are likely crucial in cancer development and progression." (PMID 41142627, 2025). "This study employs bioinformatics methods based on multiple datasets to systematically reveal the clinical significance and potential functional mechanisms of CLIC6 in different cancer types." (PMID 41142627, 2025). "In conclusion, these findings better understand CLIC6’s role in cancer and suggest new avenues for innovative immunotherapy strategies." (PMID 41142627, 2025). "Next, this study used the UALCAN database to explore the expression levels of the CLIC6 protein across different cancer tissues." (PMID 41142627, 2025). "In summary, CLIC6 genetic alterations occur in most malignant tumors and influence cancer patient prognosis." (PMID 41142627, 2025). "In summary, this study offers a novel perspective on the role of CLIC6, contributing to the advancement of innovative cancer treatment strategies." (PMID 41142627, 2025). "Research shows that CLIC6 expression is typically lower in most cancers compared to normal tissues, with distinct patterns across different stages." (PMID 41142627, 2025). "Subsequently, the GSCA database was used to analyze the impact of CLIC6 promoter methylation levels on cancer patient outcomes, including OS, PFS, and DSS." (PMID 41142627, 2025). "Subsequently, this study investigated the prognostic significance of CLIC6 across various cancer types." (PMID 41142627, 2025). "In summary, CLIC6 appears to play distinct roles in different cancers, thereby exerting varying effects on patient prognosis." (PMID 41142627, 2025). "First, this study assessed the expression levels of CLIC6 mRNA in various types of malignant tumors using the TCGA database." (PMID 41142627, 2025). "This study investigated the correlation between CLIC6 expression and CLIC6 promoter methylation levels, as well as the expression of m6A methylation-related regulatory factors, across different cancers." (PMID 41142627, 2025).
cancer (continued). "The findings of this study contribute to understanding the role of CLIC6 in cancer and emphasize that CLIC6 influences the prognosis of cancer patients, potentially serving as a target for future treatments." (PMID 41142627, 2025). "The findings showed that CLIC6 expression exhibited variability across different cancer types, with a predominantly low expression observed in the majority of cases." (PMID 41142627, 2025). "In summary, modifications in CLIC6 methylation are significant in the context of pan-cancer; however, additional functional experiments are required to substantiate its mechanistic role." (PMID 41142627, 2025). "The findings indicated that reduced expression levels of CLIC6 mRNA were correlated with a less favorable prognosis across a majority of cancer types." (PMID 41142627, 2025). "This study identified PSCA as a risk gene (hazard ratio > 1) for BRCA, while FREM1, NPY1R, CCL19 and CLIC6 were the protective genes for the cancer (hazard ratio < 1)." (PMID 39119106, 2024). "CLIC6 is also primarily expressed in cancer epithelial cells, followed by CAFs and normal epithelial cells." (PMID 39512680, 2024). "We found that the expression of CLIC4 was increased in cancer tissues; however, the mRNA expression of CLIC2 and CLIC6 was lower in HCC tissues than in non-cancer tissues." (PMID 34766585, 2021). "This indicates that CLIC6 could be a significant determinant affecting the prognosis of these cancers." (PMID 41142627, 2025). "On the other hand, the expression patterns of genes like SFTPB, LAMC2, KRT7 and CLIC6 varied significantly among different cancer types, suggesting that these genes may play context‐dependent roles." (PMID 39828988, 2025). "While CLIC6 has been linked to cancer progression, its comprehensive role across various cancers is not well comprehended." (PMID 41142627, 2025). "Therefore, this study further explored the interplay between CLIC6 mRNA expression and key m6A methylation regulators in certain cancers." (PMID 41142627, 2025). "Studies have shown that CLIC6 may serve as a regulator of potential significance in cancer biology." (PMID 41142627, 2025). "In addition, a study of paired samples from 23 types of malignant tumors revealed that CLIC6 mRNA expression was notably reduced in eight types of malignant tumor tissues (COAD, HNSC, KICH, KIRC, LIHC, LUSC, PRAD, and THCA) compared to adjacent paracancerous tissues." (PMID 41142627, 2025). "However, the significance of CLIC6 in the glycolysis in cancer patients remained unknown, and our findings suggested that this gene was implicated in the glycolysis and progression of BRCA." (PMID 39119106, 2024). "IHC analysis from the HPA dataset showed a notable increase in CLIC6 protein expression in LUAD, GBM, PAAD, TGCT, and UCEC compared to normal tissue, aligning with previous CLIC6 mRNA findings across cancers." (PMID 41142627, 2025). "Additionally, in cancers such as SKCM, LUSC, LUAD, PAAD, and HNSC, the occurrence of CNVs in CLIC6 was positively correlated with CLIC6 mRNA expression levels (P < 0.05)." (PMID 41142627, 2025). "Moreover, CLIC6, is a member of the Chloride Intracellular Channel (CLIC) family, was found to be modulated in many cancers and its expression was found to be correlated with favorable outcome and better survival." (PMID 34307159, 2021). "This study also found that CLIC6 expression was higher in early clinical pathological stages than in advanced stages among patients with BRCA, KICH, KIRP, LUAD, and THCA, suggesting that CLIC6 may influence the prognosis of these cancer patients." (PMID 41142627, 2025).
CLIC6 also shares sentences with these, for which no sentence is quoted: endometrial cancer (2 papers); Hydrocephalus (2); colon adenocarcinoma (1); diaphragmatic hernia (1); head and neck squamous cell carcinoma (1); Insulin resistance (1); Intellectual disability (1); liver cancer (1); major depression (1); neurodevelopmental disorder (1); pancreatic cancers (1); schizophrenia (1); Wolfram syndrome (1).